NFKB1 (nuclear factor kappa B subunit 1)
Diseases named in the same sentence as NFKB1 in open-access papers (continued):
Sharing a sentence is not in itself a finding about the gene and the disease.
cancer (continued). "Many studies have implicated nuclear factor E2-related factor 2 (Nrf2) and nuclear factor-κB1 (Nfkb1) in inflammation and cancer." (PMID 19050705, 2008). "Taken together, our study provides a canonical framework to understand the regulatory potential for concerted modulation of Nrf2 and Nfkb1 in inflammation and cancer." (PMID 19050705, 2008). "NFKB1 plays a pivotal role in inflammatory diseases and cancer." (PMID 40994138, 2025). "Moreover, NFKB1 is involved in regulating the self-renewal, differentiation and treatment resistance of cancer stem cells." (PMID 40666524, 2025). "Monogenic CVIDs with highest predisposition to cancer include the activated phosphoinositide 3-kinase delta syndrome (APDS), nuclear factor kappa B subunit 1 (NF-kB1) insufficiency, and signal transducer and activator of transcription 3 (STAT3) gain-of-function." (PMID 40925926, 2025). "Mice lacking NFKB1 exhibited inflammation, heightened susceptibility to DNA damage, and accelerated aging, changes known to promote cancer development." (PMID 40312983, 2025). "NFKB1 belongs to the (NF)-κB gene family and represses inflammation, aging, and cancer." (PMID 41325388, 2025). "Furthermore, we analyzed the mutation status of ASCC3, JAK1, NFKB1, SEMA5A, NR2C2, CNTF and CREB1 across pan-cancer." (PMID 40881169, 2025). "NFKB1 acts as a suppressor of cancer progression by modulating the NF-κB-related pathway." (PMID 40612864, 2025). "We have previously shown that NFKB1 increases invasibility of skin fibroblasts to cancer invasion." (PMID 39333481, 2024). "To directly identify the association of NFκB1 and RelA on MDR gene of cancer cells, we have treated EP and LP cancer cells with MDSC supernatant for a period 240 mins, keeping cancer cells without Dox as a control and then carried out ChIP assay followed by immune-precipitation." (PMID 38304256, 2023). "NF-κB induction is a key process in cancer progression and promotes NFKB1." (PMID 36980957, 2023). "Interestingly, miR-572 for which NFKB1 is the target showed significant overexpression in G1 cancer followed by a sharp decline in the remaining grades." (PMID 37233761, 2023). "These, together with unchanged NFκB1 expression may indicate either the delayed response of the cancer cells to the applied stimuli or the inhibition of the inflammatory pathway." (PMID 36296918, 2022). "Notable monogenic PIDs, whose genetic background directly predisposes to cancer, include the activated phosphoinositide 3-kinase δ syndrome (APDS), nuclear factor kappa B subunit 1 (NF-κB1) insufficiency, and Signal transducer and activator of transcription 3 (STAT3) gain-of-function syndrome." (PMID 35250968, 2022). "However, due to the low number of cases in our study (n = 6), coupled with just one early stage of cancer (pT1aN0Mx), drawing far-reaching conclusions of NFKB1 involvement in PC progression is precluded." (PMID 36555871, 2022). "Noteworthy, in both murine and human PC cells, IL30 stands out as an upstream regulator of key drivers of inflammation, immunity and cancer, such as NFKB1 and BCL2, which in human PC cells can be efficiently suppressed by CRISPR/Cas9-mediated IL30 gene deletion." (PMID 36224639, 2022). "NFKB1 and NFKB1A, subunits of NF-κB, are associated with cancer due to inflammation." (PMID 36249762, 2022). "NFKB1 forms various dimeric complexes with other subunits to activate NFkB signaling that regulates several biological processes, including inflammation, senescence, apoptosis, cell survival, and cancer progression." (PMID 34335799, 2021). "Moreover, NFKB1 has been reported to play a crucial role in attenuating the activation of the NF-κB signaling pathway, potentially revealing a new therapeutic target in inflammatory diseases and cancer." (PMID 34938730, 2021). "Multiple number of NFKB1 gene SNPs were investigated in the implication of cancer." (PMID 34672421, 2021). "NFKB1 plays a role in cancer progression and is a potential target for cancer therapy." (PMID 34335799, 2021).
cancer (continued). "The role of NFKB1 in cancer and the inflammatory pathway is well documented." (PMID 34067609, 2021). "Furthermore, NFKB1 and HIF1 expression were negatively correlated with CDK5 and TXN2 in all three cancers, while HIF1-NFKB1 showed a positive association with each other." (PMID 32033319, 2020). "A special family of transcription factors named necrosis factor kappa B (NF-ĸB) plays critical roles in cancer initiation and progression, and mRNA expression of nuclear factor kappa B subunit 1 (NF-ĸB1) has been shown to be down-regulated in multiple hematological malignancies." (PMID 31261921, 2019). "Thus, highlighting the importance of dissecting cell-specific roles of NFKB1 if we are to attempt to manipulate its function as a potential future therapy for inflammation and cancer." (PMID 30205516, 2018). "This suggests that inflammation and the NFKB1 ‘switch' could also be involved in the upregulation of CD47 expression in other cancer types, such as T-ALL, through the activation of a different CD47 cis-regulatory region." (PMID 28378740, 2017). "Allelic variants of the interleukin 1A (IL1A), interleukin 4 (IL4), nuclear factor kappa B1 (NFKB1) and protease-activated receptor 1 (PAR1) genes may influence not only the inflammatory response but also susceptibility to cancer development." (PMID 26879815, 2016). "NFKB1 is being increasingly considered as an important TF in cancer progression." (PMID 27821810, 2016). "Four putatively functional SNPs (NFκB1: rs28362491del>ins ATTG; NFκB2: rs12769316G>A; IκBα: rs2233406C>T and rs696G>A) were analyzed to evaluate their associations with NPC risk in total 1590 NPC cases and 1979 cancer-free controls." (PMID 26161396, 2015). "We therefore evaluated three polymorphisms in NFKB1 and TLR4 and their possible interaction with diet and life style factors in a prospective cohort of 1010 CRC cases and 1829 randomly selected participants from the Danish Diet, Cancer and Health Study." (PMID 25705893, 2015). "Therefore, we collected all available data to perform an updated meta-analysis that generates a precise estimation to comprehensively and objectively investigate the association between the NFKB1 promoter −94ins/del ATTG polymorphism and cancer risk." (PMID 24895544, 2014). "Protein Bcl-3, the expression of which is upregulated in both cancer cell lines, may bind to NFKB1 and NFKB2 homodimers and form complexes that function as transcriptional activators." (PMID 24037645, 2013). "Recent studies showed genetic polymorphisms of the NFKB1 and NFKBIA genes to be associated with cancer risk and severity in sporadic colorectal cancer and oral cancer, but their possible associations with predictions of risk and prognosis of HCC remain poorly investigated." (PMID 23457512, 2013). "Further, we streamlined our study to five data sets, which were representative of the most distinct inflammation/injury and cancer signatures of interest and constructed a canonical first-generation regulatory network for Nrf2 (Nfe2l2) and Nfkb1, representing 59 nodes and 253 potential interactions." (PMID 19050705, 2008). "The identification of PPAR in the promoter regions of Nrf2 and Nfkb1 in this study, thus, reinforces the significance of these transcription factors and provides a possible mechanistic pathway for crosstalk in inflammation and cancer." (PMID 19050705, 2008). "The results from our current in silico study may strengthen the possibility that scientists could, in the future, consider pursuing Nrf2, Nfkb1 and MAPKs as potential targets in early drug discovery screens for the management of inflammation and cancer." (PMID 19050705, 2008). "Finally, we present a gestalt pictorial overview of our current knowledge of concerted modulation of Nrf2 and Nfkb1 based on the data from this study and our extensive experience in cancer chemoprevention." (PMID 19050705, 2008).
cancer (continued). "Therefore, the STAT/gp130/OSMR/JAK feedforward loop and NF-κB (REL, NFKB1) may operate combinatorially in cancer." (PMID 32102440, 2020). "A common insertion/deletion polymorphism in the promoter region of the NFKB1 gene elicits a regulatory effect on the NFKB1 gene and an increasing number of studies have assessed the association between the NFKB1 −94ins/del ATTG promoter polymorphism and cancer risk." (PMID 27463002, 2016). "Recently, many studies have tested the association between different forms of cancer and functional variants of genes responsible for the inflammatory process, such as interleukin 1A (IL1A), interleukin 4 (IL4), nuclear factor kappa B1 (NFKB1) and protease-activated receptor 1 (PAR1)." (PMID 26879815, 2016). "Recently, a common insertion/deletion (-94 insertion/deletionATTG rs28362491) polymorphism in the NFκB1 promoter region and a 3′ -untranslated region (3′UTR) polymorphism 2758A>G (rs696) in NFκBIA were observed to be significantly correlated with inflammatory bowel disease and cancers." (PMID 21738780, 2011). "Functional inference also indicated enrichment of cancer-related orthologs such as LKB1, NFKB1, ITGAV, and TRAF4." (PMID 41356699, 2025). "The TF-protein NFKB1 (a regulator of GUCA2A, CA4, CEMIP and MS4A12) is a suppressor of inflammation, ageing and cancer." (PMID 36991484, 2023). "Quantitative analysis further affirmed the activation of NFKB1 and RELA in IM and cancer cells, signifying their up‐regulation as a pivotal early event in the process of GC progression." (PMID 37983931, 2023). "CYLD and SMPD2 were characteristics of G2 cancer, and TNFR1, TNFR2, NFKB1, TAB2, and USP4 for G3 cancer." (PMID 37233761, 2023). "CircRNA profiling by microarray revealed a potential role of circ_IPCEF1 in PTC and showed interactions with four cancer-related genes, “CASR, CDC25B, NFκB1, and SHOC2” through sponging miR-3619-5p." (PMID 36230649, 2022). "Their active ingredients act on key targets such as VEGFA, VWF, IL6, TNF, and NFKB1, therefore regulating AGE-RAGE, FA, Toll-like receptors, PI3K/Akt, NF-κB, apoptosis, and cancer signaling pathways." (PMID 35096102, 2022). "In the collected clinical specimens, qPCR results revealed notably lower CYCS and NFKB1 expression and notably higher IKBKB and TRADD expression in cancer tissues than in healthy paracarcinoma ones (P < 0.05)." (PMID 35502302, 2022). "Relative to IOSE80, all cancer cell lines exhibited upregulated expression levels of LINC00494 and NFκB1 as well as downregulated expression level of FBXO32." (PMID 33585183, 2020). "Suppression of RELA, NFKB1 and NEMO inhibited “circular chemo-repellent induced defects” (CCIDs), which form when cancer cells cross the lymphatic vasculature, by ~20–30%." (PMID 26513020, 2015). "For this gene set, we found significant enrichment of annotation for BC, PC, cancer, and MET, as well as regulation of gene expression by AP1, STAT1, STAT3, and NFKB1." (PMID 24612742, 2014). "We find significant evidence of the OVOL, AP1, STAT1, STAT3, and NFKB1 TFs having important roles in MET, and more broadly in cancer." (PMID 24612742, 2014).
cancer (continued). "In the spleen, 8/84 cancer-related genes were affected in FLT mice compared to AEM controls (P<0.05; up: Cdkn2a; down: Birc5, Casp8, Ctnnb1, Map2k1, Mdm2, NFkB1, Pdgfa)." (PMID 24069384, 2013). "Jun, CSF2 and IL-8 showed increased expression in IMR90 cells, whereas, NFκB1, NFκBIA, FN1 (fibronectin 1), GADD45A, BIRC2, TMEPAI (prostate androgen induced RNA) and CEBPB (CCAAT/enhancer binding protein) were up regulated in cancer cells." (PMID 22321936, 2012). "Topological analysis of the combined networks revealed that many predicted interactions are disrupted in cancer, with E2F1, SP3 and NFκB1 emerging as major regulators." (PMID 22548828, 2012). "In conclusion, JUN, NFKB1 and SP1 may jointly maintain the characteristics of cancer stem cells by regulating the stemness maintenance and telomerase activity of cancer stem cells, thus influencing the progression, treatment resistance and recurrence of BC." (PMID 40666524, 2025). "In the Hong Kong cohort, NFKB1/RELA and PIEZO1 expression in identical samples were assessed through IHC, and their protein levels showcased a direct correlation when scoring the positive cancer cell percentage (n = 128)." (PMID 37983931, 2023). "When comparing the candidates to the non-candidate genes (those non-NFκB/TNF hallmark genes receiving no votes across all cancer types), the candidates displayed higher similarity to the canonical pathway genes TNF, RELA, NFKB1, and RELB." (PMID 37475016, 2023). "Our prior results demonstrated that the key components of the canonical NF‐κB signaling pathway, NFKB1 and RELA, were significantly upregulated at the protein level in GC and played a crucial role in the transition from inflammation to cancer." (PMID 37983931, 2023). "As shown, the expression of NFKB1, NFKB2, REL, RELA, and RELB varied in different cancer types." (PMID 35036435, 2022). "We identified four proteins (p21, NFkB1, MAPK1, and Sirt2) as potential target gene candidates regulated by SRSF3 through cell stress array analysis, correlation analysis, and expression levels between cancer and normal tissues." (PMID 36344491, 2022). "Numerous meta-analyses have addressed the relationship between NFκB1 promoter -94ins/del ATTG polymorphism and cancer risk, although their findings are not entirely consistent." (PMID 34758846, 2021). "In addition, the link shown by COSMOS between NFKB1 and MYC can have implications for the treatment of ccRCC, due to its pivotal role in arsenite (a drug used in chemotherapy) treatment of cancer." (PMID 33502086, 2021). "The results showed that there were 9 active components acting on key targets such as VEGFA, VWF, IL6, TNF, NFKB1, respectively, as well as regulating signaling pathways such as AGE-RAGE, FA, Toll-like receptor, PI3K/Akt, NF-κB, apoptosis and cancer signaling pathways." (PMID 33424592, 2020). "Given the complex and diverse nature of cancer as a disease, it is not surprising that the function of NFKB1 can differ substantially in a cell, organ, and cancer specific manner." (PMID 30205516, 2018). "Interestingly, NEMO (IKBKγ) (FC 1.11), IKBKB (FC 0.94), NFκB1 (FC 0.92) and RELA (FC 1.12) were only slightly changed in carcinoma tissue compared to normal mucosa." (PMID 29188362, 2018). "Interestingly, STAT1[Gene ID: 6772], NFKB1[Gene ID: 4790] and JUN[Gene ID: 3725] genes, three crucial signaling molecules in cancer cells, have been further identified as common targets of the three compounds." (PMID 26359356, 2015). "On the contrary, NFκB1 is activated by the ATM kinase following irradiation and confers resistance to apoptosis which can be abrogated by blocking NFκB1, leading to cytotoxicity and caspase 3 activation in cancer cell lines after irradiation." (PMID 25005804, 2014).
cancer (continued). "We found that NFKB1 −94 ATGG1/ATGG2, −94 ATGG2/ATGG2, and the combination of −94 ATGG1/ATGG2 and ATGG2/ATGG2 genotypes NFKBIA −826 T (CT+TT) and −881 G (AG+GG) allelic carriages, were more prevalent in OSCC patients than in non-cancer participants." (PMID 22509384, 2012). "Because kaempferol sensitizes OVCAR-3 cancer cells' response to cisplatin treatment, the effect on gene expression by cisplatin and/or kaempferol was further evaluated by analyzing mRNA levels of ABCC1, ABCC5, ABCC6, NFκB1, cMyc and CDKN1A genes." (PMID 20459793, 2010). "To gather information about p300 and CBP in human cancer, we examined The Cancer Genome Atlas (TCGA) dataset and found significant correlations between EP300 or CBP mRNAs and genes identified by our integrative RNA-seq and ATAC-seq analyses, including RELA, STAT1, NFKB1, IFNGR2, and NLRC5." (PMID 33602823, 2021). "The fact that miR-9 is positively regulated by inflammation-induced canonical NF-κB (RelA/65-p50) signaling, taken together with the finding that miR-9 targets NFKB1 (p105/p50), suggests a negative feedback loop mechanism fine tuning the inflammatory response with an impact in cancer." (PMID 29601548, 2018). "By literature mining we identified some interesting genes (as STAT3, HIF1a, NFKB1, KRAS) that have been reported to play an important role in biological processes as inflammation, EMT, coagulation and angiogenesis, which are at the basis for cancer and cardiovascular diseases." (PMID 29703138, 2018). "Finally, through gene expression analysis, we identified signaling molecules that might contribute toward TRAIL and MSC-TRAIL resistance in CD133+ CSCs, and uncovered NFKB1, BAG3, MCL1, GADD45A, and HRK as potential anti-cancer genes that could increase sensitivity of NSCLC to MSC-TRAIL therapy." (PMID 31466290, 2019). "Just as in NFKB1 expression, NFKB2 mRNA was found as the highest levels in PC, but the observed upregulation between normal and cancer samples was not as high (ca. 3.5 times higher than in control and normal foreskin)." (PMID 36555871, 2022). "For cisplatin/kaempferol treatments on OVCAR-3 cancer cells, the mRNA levels of ABCC1, ABCC5, and NFkB1 did not change." (PMID 20459793, 2010).